U2 (U2 spliceosomal RNA )
Synonyms: LOC124904136
Gene: Small nuclear RNA gene on chromosome 17 (43,241,180 to 43,241,370, reverse strand). Ensembl gene ENSG00000273709.
Gene Ontology:
Molecular function: pre-mRNA branch point binding
Biological process: mRNA branch site recognition
Cellular component: U2 snRNP
Homologues: Orthologues: chimpanzee U2 (100% identical), macaque U2 (100% identical), dog U2 (99% identical), pig U2 (48% identical), rat LOC120094029 (36% identical). Paralogues in human: U2 (100% identical), RNU2-2 (96% identical), U2 (95% identical), RNU2-3P (93% identical), RNU2-4P (93% identical), RNU2-17P (90% identical), RNU2-6P (90% identical), RNU2-48P (89% identical), RNU2-52P (89% identical), RNU2-59P (89% identical), RNU2-25P (87% identical), RNU2-26P (87% identical), and 68 more.